CLK2 (CDC like kinase 2)
Diseases named in the same sentence as CLK2 in open-access papers (continued):
Sharing a sentence is not in itself a finding about the gene and the disease.
Anxiety (1 paper, 2023). Intense feelings of nervousness, tension, or panic often arise in response to interpersonal stresses. "Among the aspects of behavior studied in the present study (spatial learning and memory capacity, locomotion, and anxiety), the deletion of CLK2 in GABAergic neurons has only impacted anxiety-like behavior in the female (Vgat-Cre; Clk2loxP/loxP) mice group." (PMID 37635967, 2023). "Interestingly, only females (not males) GABAergic neuron-specific CLK2 deficient mice exhibited anxiety-like behavior changes compared to their gender control." (PMID 37635967, 2023). "In addition, loss of CLK2 in GABAergic neurons changes anxiety-like behavior only in female mice without compromising cognition or memory function." (PMID 37635967, 2023). "Discrepancies in anxiety-like behavior found in females but not males suggest a potential sex dimorphism under the participation of CLK2 in behavioral regulation." (PMID 37635967, 2023). "To measure locomotor activity and emotionality and assess the anxiety-like behavior of mice lacking CLK2 in GABAergic neurons at young adulthood age, we performed the OFT." (PMID 37635967, 2023). "Interestingly, deleting CLK2 in GABAergic neurons changed anxiety-like behavior only in females, not males." (PMID 37635967, 2023). "Our data suggest that the absence of CLK2 in GABAergic neurons may contribute to decreasing anxiety-like behavior and alter the emotional behavior only in females." (PMID 37635967, 2023).
Ataxia (1 paper, 2023). Ataxia refers to impaired coordination of voluntary muscle movement. "Finally, in a patient who suffers from mild ataxia with oculomotor apraxia, the de novo novel CLK2 c.1120T>C variant was found." (PMID 38003592, 2023).
autoimmune disease (1 paper, 2024). A disorder resulting from loss of function or tissue destruction of an organ or multiple organs, arising from humoral or cellular immune responses of the individual to their own tissue constituents. "In addition, our findings suggested that the loss or inactivation of CLK2 could lead to the subsequent activation of p65 and chronic inflammation, thereby contributing to the development of cancer and autoimmune diseases." (PMID 38724505, 2024).
bladder cancer (1 paper, 2022). "Then, 9 target genes that were differentially expressed between bladder cancer and normal samples were screened (FDR < 0.05), in which upregulated expression of RHBG, PAQR6, CLK2, KRTCAP2, FLAD1, HCN3 were correlated with bad survival of patients with bladder cancer." (PMID 36186809, 2022).
cervical squamous cell carcinoma (1 paper, 2023). A squamous cell carcinoma arising from the cervical epithelium. "Increased expression of CLK2 was correlated with poor clinical outcomes in cervical squamous cell carcinoma and endocervical adenocarcinoma (CESC), COAD and KIRC." (PMID 37029108, 2023).
esophageal squamous cell carcinoma (1 paper, 2025). Esophageal squamous cell carcinoma (ESCC) is a type of esophageal carcinoma (EC) that can affect any part of the esophagus, but is usually located in the upper or middle third. "Previous studies have indicated that in esophageal squamous cell carcinoma, PABPC1 fosters both angiogenesis and malignant progression by inducing IFI27 mRNA stability, and PABPC1 de‐ubiquitinated by USP10 promotes the stability of CLK2 mRNA to facilitate the development of pancreatic cancer." (PMID 40013670, 2025).
Glucose intolerance (1 paper, 2023). Glucose intolerance (GI) can be defined as dysglycemia that comprises both prediabetes and diabetes. "We speculate that glucose intolerance in the females may be partially due to impaired hypothalamic insulin signaling caused by the deletion of CLK2 in GABAergic neurons." (PMID 37635967, 2023).
renal carcinoma (1 paper, 2024). A carcinoma arising from the epithelium of the renal parenchyma or the renal pelvis. "On the other hand, in renal cancer, CLK2 strongly correlated with poor prognosis (p = 3 × 10−8), whereas DYRK1B was indicative of prolonged survival (p = 9 × 10−4)." (PMID 38398225, 2024).
viral infections (1 paper, 2024). "Compared with their wild-type littermates, Clk2-deficient mice had increased serum levels of inflammatory cytokines after viral infection and showed increased resistance to virus-induced death." (PMID 38724505, 2024). "In summary, these findings underscore the complex regulatory role of CLK2 in the inflammatory response, potentially exhibiting dual effects in different inflammatory diseases or virus infection." (PMID 38724505, 2024). "Our findings demonstrate that knockout of CLK2 in human and mouse cells increases the induction of inflammatory and antiviral genes and impairs viral replication and viral infection." (PMID 38724505, 2024). "Furthermore, overexpression of CLK2 did not influence the cytosolic localization of p65 in resting cells but resulted in an exclusive reaction between nuclear p65 and CLK2 after viral infection." (PMID 38724505, 2024). "To test this hypothesis, we administered the CLK2 inhibitor TG003 to human cells and mice and observed clear effects on viral infection in vitro and in vivo and the promotion of IMQ-induced inflammatory lesions in vivo." (PMID 38724505, 2024).
cancer (30 papers, 2015 to 2025). A tumor composed of atypical neoplastic, often pleomorphic cells that invade other tissues. "We already mentioned that cancer associated hyperactivity of CLK2 results in hyperphosphorylation od CFIm68 and so inhibits its function." (PMID 39321865, 2025). "Catalytically active CLK2 can regulate pre‐mRNA AS and is closely associated with various diseases, particularly in the pathogenesis of cancers." (PMID 38723164, 2024). "Furthermore, when assessed against the most closely related kinases also implicated in cancer, the frontrunner compounds revealed additional inhibitory activity against Haspin and Clk2." (PMID 38893153, 2024). "CLK2 is expressed ubiquitously, and increasing evidence has found that CLK2 is closely associated with various diseases, such as neurodegenerative diseases and cancers." (PMID 35860803, 2022). "As we known, CLK2 gene encodes a type of protein kinase that phosphorylates serine/arginine-rich proteins (SR proteins), which plays essential roles in the AS of pre-mRNA in various cancers." (PMID 35860803, 2022). "Lor and Cir, two clinically investigated inhibitors of CLK2 and other CLKs/DYRKs have anti‐cancer activity in PC cell lines and lead to ARFL/ARV7 protein downregulation." (PMID 39258426, 2025). "CLK1 and CLK2 are upregulated in various cancers including breast, colorectal, prostate, and glioblastoma." (PMID 38753413, 2024). "It is involved in splicing of Wnt pathway genes, and Wnt has been shown to be responsible for the CLK2 induced cancer progression." (PMID 38499482, 2024). "The most potent analogues were further tested against three highly homologous kinases, Clk2, Clk3, and Haspin, which are equally involved in several types of cancers." (PMID 38893153, 2024). "For example, CLK2 inhibitor T-025 inhibits tumor cell proliferation via inducing exon skipping in MYC-driven cancers." (PMID 35860803, 2022). "Our DDMC results suggest that downregulation of NEKs and CLK2 promote cilia disassembly and migration in cancer cells, respectively, while CK1 activity correlates with tumor-specific signaling regulating cell cycle." (PMID 35360705, 2022). "Up to date, several CLK2 inhibitors have been investigated in experiment or clinical traits in various cancers." (PMID 35860803, 2022). "Second, the poor application exists in different cancers, which suggests that CLK2 plays different roles in different tumors." (PMID 35860803, 2022). "The CLK2 gene is amplified in a significant proportion of breast tumours and its downregulation inhibits cancer cell growth in cell culture and xenografts." (PMID 33846420, 2021). "MYC amplification and high CLK2 expression in cancer cells are considered predictive of the response to a CLK inhibitor." (PMID 33064779, 2020). "We demonstrated that T‐025 caused common alternative SEs in cancer cell lines and showed that there was more effective growth inhibition in cancer cell lines with high CLK2 expression or with MYC activation." (PMID 29769258, 2018). "We identified CLK2 as a novel downstream molecule of p38, and the CLK2 inhibitor is currently under investigation for the futural clinical trials to treat degenerative diseases and cancers." (PMID 38617434, 2024). "RNA-Seq data provided by the TCGA has shown that CLK2 is overexpressed in many cancer types." (PMID 37029108, 2023). "In conclusion, CLK2 might be an ideal therapeutic target and prognostic marker for cancer treatment." (PMID 37029108, 2023). "Therefore, it is essential to explore the potential molecular mechanisms of CLK2 in different cancers." (PMID 35860803, 2022). "Second, we evaluated T3 in a panel of 60 solid cancer cell lines and found that the growth inhibition profile of T3 was similar to that of T‐025 (r2 = 0.783, Fig EV4D), and cancer cell lines with a high CLK2 protein level also showed a higher growth inhibitory response to T3 (Fig EV4E)." (PMID 29769258, 2018).
cancer (continued). "To evaluate the hypothesis generated from the bioinformatics analysis, we first assessed the protein level of CLK2 in 56 various cancer cell lines because the protein level of CLK2 is also regulated by ubiquitination‐dependent degradation." (PMID 29769258, 2018). "Taking also into account that, besides CK2, it inhibits PIM-1 (a very important and innovative target in cancer therapy), CLK2, and, with lower efficacy, also DYRK1A, we believe that TDB displays good features to be considered for future clinical experimentation." (PMID 26558259, 2015). "In addition, whether CLK2 has a similar role in other cancers, remains to be studied." (PMID 38617434, 2024). "Recognizing the significance of CLK2 in cancers, we initiated a SBVS campaign to identify potential CLK2 inhibitors." (PMID 38723164, 2024). "A previous study has demonstrated that CLK2 inhibitor T-025 has antitumor efficacy in many tumors, especially in MYC-driven cancers." (PMID 35860803, 2022). "In addition, only five out of 546 AS events tested in several cancer cell lines were commonly regulated by T‐025 and MYC, suggesting that CLK2 and MYC regulated different splicing‐related genes." (PMID 29789342, 2018). "Another hypothesis is that CLK2 and MYC cooperatively regulate pre‐mRNA biosynthesis and maturation to improve the survival of cancer cells." (PMID 29769258, 2018). "To apply our hypothesis that CLK2‐high and MYC‐amplified cancers were more sensitive to T‐025 in clinical stratification, we re‐assessed the result of our growth inhibition panel on the basis of original organ type and evaluated public clinical data." (PMID 29769258, 2018).
tumor (21 papers, 2014 to 2025). "In TNBC, the aberrant regulation of AS by CLK2 emerges as a critical factor influencing tumor progression." (PMID 38723164, 2024). "The pan-CLK inhibitor SM08502 displays anti-tumor activity in gastrointestinal cancer models, while the potent CLK2 inhibitor T-025 demonstrates anti-tumor efficacy in an allograft model of MYC-driven breast cancer." (PMID 38753413, 2024). "Functional assays showed that CLK2 protected OC cells from platinum‐induced apoptosis and allowed tumor xenografts to be more resistant to platinum." (PMID 38617434, 2024). "The tumor tissue also revealed an increase in CLK2 mRNA expression, whereas the KHDRBS3 mRNA expression was lower, compared to normal tissue." (PMID 38132164, 2023). "We notice an increased CLK2 mRNA expression in LUAD and LUSC tumors compared to normal tissue, and that CLK2 mRNA expression is elevated in tumor subpopulations with low PD-L1 mRNA expression relative to high expression." (PMID 38132164, 2023). "We compared the expression levels of IGF2BP3, P4HB, RAC3 and CLK2 in TCGA BCa tissues and normal tissues, and the results showed that all four genes were significantly upregulated in tumor tissues." (PMID 38299148, 2023). "We noticed an increased CLK2 mRNA expression in tumor subpopulations with low PD-L1 mRNA expression." (PMID 38132164, 2023). "Antibody HPA055366 staining for CLK2 in normal kidney tissue was medium, whereas it was low in tumor tissue." (PMID 34420511, 2022). "We further explored the differential AS event prevalence between normal and tumor samples and the relationship between CLK2 expression and PSI value of differential splicing genes." (PMID 35860803, 2022). "Immunohistochemical analysis of tumor sections obtained from CLK2-knockdown tumors for Ki-67 demonstrated decreased expression of cells proliferating, whereas sections obtained from vector-infected mice had high expression of Ki-67." (PMID 27050366, 2016). "In these patients, if the state of BRCAness could be achieved, their tumor cells would be resensitized to chemotherapy, indicating that the CLK2 inhibitor may be also effective." (PMID 38617434, 2024). "Furthermore, CLK2 induced tumor cell adhesion and thereby promotes local invasion of CRC." (PMID 35860803, 2022). "Additionally, tumor volumes were significantly smaller in CLK2-knockdown mice than in controls." (PMID 27050366, 2016). "Targeting CLK2 in combination with PARP inhibitor is synergistic in inducing more severe DNA damage in cisplatin‐resistant OC cells, attenuating tumor growth, and prolonging survival time in mice bearing patient‐derived xenografts (PDXs)." (PMID 38617434, 2024). "Previous research suggests that simultaneous inhibition of both CLK2 and CLK3 results in a more pronounced anti‐tumor effect, highlighting their significance as potential therapeutic targets." (PMID 38723164, 2024). "A clearer understanding of the underlying mechanism of action of T‐025 inhibitor as a function of the tumor type, as well as the interplay between MYC and CLK2, is now needed." (PMID 29789342, 2018). "In the xenograft models, expression of the proliferation maker Ki-67 decreased in CLK2-knockdown mice implanted with GSC11 and GSC272 tumor cells." (PMID 27050366, 2016). "To examine the synergistic efficacy of CLK2 and PARP inhibition for increasing chemosensitivity in vivo, we utilized PDX models, which recapitulate patient tumor heterogeneity and histopathology and have been used to predict the clinical response to chemotherapy." (PMID 38617434, 2024). "Similarly, cluster 15 is dramatically upregulated in NAT versus tumor samples, contributes toward correctly classifying NAT samples, and DDMC predicts CLK2 to be the most promising candidate for regulating its activation." (PMID 35360705, 2022).
tumor (continued). "Both in vitro and in vivo data demonstrated that inhibition of CLK2 reversed platinum resistance of OC cells, and, when combined with a PARP inhibitor, synergistically suppressed tumor growth in the BRCA1WT PDX model but not the BRCA1MUT PDX model." (PMID 38617434, 2024).
Hematological cancers (2 papers, 2018). "Hematological cancers also seem to benefit from CLK2 inhibition, although CLK2 or MYC did not sensitize these cells to T‐025, thus indicating that alternative mechanisms account for such effects." (PMID 29789342, 2018).
infection (2 papers, 2016 to 2024). The state of being infected such as from the introduction of a foreign agent such as serum, vaccine, antigenic substance or organism. "Stable knockdown of CLK2 expression in GSCs by infection with specific shRNA-containing lentiviruses abrogated CLK2 expression in the cells infected with shRNA2 construct compared to those infected with the shRNA1 construct." (PMID 27050366, 2016).
CLK2 also shares sentences with these, for which no sentence is quoted: degenerative diseases (3 papers); autism (1); Brain atrophy (1); brain cancer (1); diabetes (1); hepatoma (1); Hyperglycemia (1); immune diseases (1); Insulin resistance (1); intestinal cancer (1); kidney cancer (1); knee osteoarthritis (1); lymph node metastasis (1); melanoma (1); Oculomotor apraxia (1); ovarian carcinoma (1); pancreatic cancer (1); Phelan-McDermid syndrome (1); prostate tumor (1); scleroderma (1); skin cancer (1); tendinitis (1); tendinopathy (1); triple-negative breast carcinoma (1).